ADCK2 (aarF domain containing kinase 2)
Description:
The function of this protein is not yet clear. It is not known if it has protein kinase activity and what type of substrate it would phosphorylate (Ser, Thr or Tyr) (Probable). Involved in the mitochondrial import of CoQ precursors, plays a role in muscle mitochondrial function and fatty acid beta-oxidation.
Synonyms: AARF; MGC20727
Tractability: Antibody: UniProt predicts a signal peptide or a membrane-spanning region. PROTAC: ubiquitination databases record sites on it; its protein half-life has been measured.
Gene: Protein-coding gene on chromosome 7 (140,672,885 to 140,696,261, forward strand). Ensembl gene ENSG00000133597.
Subcellular location: Mitochondrion; Membrane
Subcellular location (Human Protein Atlas): Centrosome; Cytosol
Gene Ontology:
Molecular function: protein binding
Biological process: regulation of ubiquinone biosynthetic process
Cellular component: mitochondrion; membrane
Genetic constraint (gnomAD): Loss-of-function variants: 37 observed, 52.88 expected, observed/expected ratio (o/e) 0.7, 90% interval 0.54 to 0.92. The upper end of that interval is the gene's LOEUF score, 0.92, which puts it in group 3 of 6, group 1 being the genes least tolerant of losing a copy. Missense variants: 695 observed, 794.15 expected, observed/expected ratio (o/e) 0.88, 90% interval 0.82 to 0.93. Synonymous variants: 321 observed, 346.39 expected, observed/expected ratio (o/e) 0.93, 90% interval 0.85 to 1.02.
Homologues: Orthologues: chimpanzee ADCK2 (99% identical), macaque ADCK2 (96% identical), dog ADCK2 (80% identical), pig ADCK2 (80% identical), mouse Adck2 (74% identical), rat Ndufb2 (72% identical), guinea pig ADCK2 (70% identical), rabbit ADCK2 (67% identical), tropical clawed frog adck2 (50% identical), zebrafish adck2 (49% identical), Caenorhabditis elegans Y32H12A.7 (29% identical). Paralogues in human: ADCK1 (16% identical), ADCK5 (15% identical), COQ8B (15% identical), COQ8A (13% identical).
Diseases named in the same sentence as ADCK2 in open-access papers:
ADCK2 is named in the same sentence as 25 diseases in open-access papers, as found by Europe PMC text mining. Sharing a sentence is not in itself a finding about the gene and the disease. The quoted sentences say what the papers report.
breast carcinoma (4 papers, 2022 to 2025). "A 2022 study reported missense mutations in ADCK2 in 9.4% of breast cancer patients, whereas such mutations were relatively rare in studies of other cancers, occurring in 0–1% of endometrial carcinomas and up to 3.5% of uterine carcinomas." (PMID 40565246, 2025). "A functional viability profile study in breast cancer has identified ADCK2 as a key gene for breast cancer cell survival." (PMID 36439873, 2022). "In ER+ breast cancer cells, the effect of ADCK2 on survival is mediated by its interaction with the estrogen receptor ERalpha and thereby altered estrogen signaling." (PMID 35205819, 2022). "ADCK2 protein expression has been reported to be elevated in luminal A compared to luminal B breast cancers." (PMID 36085291, 2022). "Lately, high ADCK2 protein expression has been proposed to be a marker for an improved therapeutic response during breast cancer neoadjuvant treatment." (PMID 36085291, 2022). "ADCK5 is upregulated in many cancers, and upregulation of ADCK2 promotes the survival of luminal breast cancer cells." (PMID 35205819, 2022). "Markedly, elevated ADCK2 expression has been observed in luminal A breast cancer patients, with evidence indicating that estrogen receptor (ER)-positive breast cancer cells may depend on ADCK2 for survival." (PMID 40565246, 2025). "In breast cancer, ADCK2 expression has been correlated with tumor size and may serve as a predictive marker for treatment response (N = 40 or 37)." (PMID 40565246, 2025). "More importantly, ADCK2 co-immunoprecipitated with ERα in breast cancer cells." (PMID 36439873, 2022). "Furthermore, ADCK2 expression correlates with cancer cell proliferation and motility and a higher expression in breast cancer went along with a better tumor shrinkage after long-term NAET (Nambudripad’s Allergy Elimination Technique) treatment." (PMID 35205819, 2022). "ADCK2 is important for estrogen-induced breast cancer cell progression." (PMID 36439873, 2022).
Mitochondrial myopathy (4 papers, 2019 to 2024). "ADCK2 haploinsufficiency-mediated mitochondrial coenzyme Q deficiency in skeletal muscle causes mitochondrial myopathy associated with defects in beta-oxidation of fatty acids, aged-matched metabolic reprogramming, and defective physical performance." (PMID 35936917, 2022). "A nonsense mutation in one ADCK2 allele led to the development of severe mitochondrial myopathy in a human patient that appeared responsive to CoQ supplementation." (PMID 31480808, 2019). "Here, we report that haploinsufficiency of ADCK2, a member of the aarF domain-containing mitochondrial protein kinase family, in human is associated with liver dysfunction and severe mitochondrial myopathy with lipid droplets in skeletal muscle." (PMID 31480808, 2019). "Haploinsufficiency of ADCK2 in humans leads to adult‐onset physical incapacity with reduced mitochondrial CoQ levels in skeletal muscle, resulting in mitochondrial myopathy and alterations in fatty acid β‐oxidation." (PMID 39354863, 2024). "The data showed that Adck2+/− mice exhibited impaired fatty acid oxidation, liver dysfunction, and mitochondrial myopathy in skeletal muscle resulting in lower physical performance." (PMID 31480808, 2019).
osteosarcoma (4 papers, 2012 to 2025). A usually aggressive malignant bone-forming mesenchymal neoplasm, predominantly affecting adolescents and young adults. "Knockout studies of ADCK2 in prostate and osteosarcoma cells have demonstrated a reduced impact of tumor necrosis factor-alpha (TNFα) on hypoxia-inducible factor 1-alpha (HIF-1α), suggesting a potential role for ADCK2 in hypoxia-driven tumor progression." (PMID 40565246, 2025). "In osteosarcoma and prostate cancer cells, ADCK2 was found to promote the TNFα-mediated accumulation of HIF-1α stability, which, in turn, is associated with the proliferation and survival of cancer cells." (PMID 35205819, 2022). "A functional genomics screen study has shown that TNFα-induced ADCK2 expression in human osteosarcoma cells and prostate cancer cells inhibited ROS production, and it was required for HIF-1α stability." (PMID 36439873, 2022). "Furthermore, the expression of ADCK2 was demonstrated to be directly modulated by TNFα in U2OS osteosarcoma cells." (PMID 40565246, 2025). "This screen determined that depletion of ADCK2, PRKAR2B, TRIB2 and TRPM7 most significantly downregulates nuclear accumulation of HIF-1α in response to the treatment of osteosarcoma cells." (PMID 22355351, 2012). "On the other hand, depletion of PRKAR2B, ADCK2, TRPM7, and TRIB2 significantly decreases the effect of TNFα on HIF-1α stability in osteosarcoma and prostate cancer cell lines." (PMID 22355351, 2012).
Adult onset (2 papers, 2019 to 2024). Onset of disease manifestations in adulthood, defined here as at the age of 16 years or later. "ADCK2 haploinsufficiency in humans produces adult‐onset myopathy with CoQ deficiency, accelerated physical incapacity and defective mitochondrial lipid metabolism." (PMID 39354863, 2024). "In conclusion, ADCK2 haploinsufficiency caused an adult onset myopathy with CoQ deficiency, and an overall defect in mitochondrial lipid metabolism, with incomplete penetrance." (PMID 31480808, 2019).
Insulin resistance (2 papers, 2022 to 2024). Increased resistance towards insulin, that is, diminished effectiveness of insulin in reducing blood glucose levels. "Altogether, these results indicated that Adck2+/− mice on an ad libitum diet exhibit higher insulin resistance and impaired glucose homeostasis, but when fed under CR conditions, insulin resistance is reverted." (PMID 35936917, 2022).
liver dysfunction (2 papers, 2019 to 2024). "CoQ deficiency, though not very severe, is proposed to be causative of the Adck2+/− mouse myopathy and liver dysfunction, based on the observation that both the human patient and the Adck2+/− mouse mutant appear to respond to CoQ10 treatment." (PMID 38722242, 2024). "A heterozygous nonsense mutation in ADCK2 that led to severe myopathy and liver dysfunction has been identified in a human patient with histological signs of mitochondrial myopathy associated with lipid storage in skeletal muscle." (PMID 38722242, 2024).
melanoma (2 papers, 2022 to 2025). A malignant, usually aggressive tumor composed of atypical, neoplastic melanocytes. "In our study, we showed that higher levels of intratumoral ADCK2 benefit patient survival, while a low expression of ADCK2 was associated with a higher motility and a dedifferentiated state of melanoma cells, which facilitates metastasis." (PMID 35205819, 2022). "In the context of melanoma, ADCK2 emerges as a crucial regulator of cell motility, a vital component in the processes of tumorigenesis and metastasis." (PMID 40565246, 2025). "The exact mechanism of how ADCK2 is influencing the viability of melanoma cells needs to be further investigated." (PMID 35205819, 2022). "Since knocking down ADCK2 significantly altered the migration capacity of melanoma cells, we also performed a wound healing migration assay after knocking down MYL6 in OE ADCK2 cells." (PMID 35205819, 2022). "Montagnani and colleagues predicted ADCK2 as a metastasis-associated gene in melanoma, especially in BRAF-mutated melanoma." (PMID 35205819, 2022). "In this study, we showed that altering the expression of ADCK2 affected the cell viability and the migrative and invasive capacity of melanoma cells." (PMID 35205819, 2022). "Our results show that a reduction in ADCK2 expression rendered melanoma cells more migrative and invasive." (PMID 35205819, 2022). "With a knockdown approach, we demonstrated that ADCK2 has a slight effect on cell viability but a great effect on the migration of several melanoma cell lines." (PMID 35205819, 2022). "This assumption was supported by the finding that the pigmentation of melanoma cells was reduced upon ADCK2 knockdown." (PMID 35205819, 2022). "In our study, we were able to show that ADCK2 had a strong effect on the motility of melanoma cells." (PMID 35205819, 2022). "In order to unravel the mechanism of how ADCK2 altered the migrative capacity of melanoma cells, we performed a gene expression analysis of three melanoma cell lines upon ADCK2 knockdown." (PMID 35205819, 2022). "Knocking down ADCK2 resulted in enhanced cell migration of melanoma cells." (PMID 35205819, 2022). "Our results could give new insights into melanoma metastasis, and ADCK2 could qualify as a prognostic marker or a target for melanoma therapy in the future." (PMID 35205819, 2022). "Next, we assessed if ADCK2 also affects the migration and invasion capacity of melanoma cells." (PMID 35205819, 2022). "In this study, we investigated the role of ADCK2 in melanoma." (PMID 35205819, 2022). "We observed a significantly lower expression of the melanocyte markers TYR and TRP1 and a higher expression of the NCC marker p75, which leads to the assumption that a knockdown of ADCK2 led to a dedifferentiation of melanoma cells, prompting them to adopt a more aggressive phenotype." (PMID 35205819, 2022). "The fact that a lower intratumoral expression of ADCK2, as well as MYL6, in melanoma is connected with a poor prognosis for melanoma patients allows the conclusion that ADCK2 might be a tumor suppressor in melanoma." (PMID 35205819, 2022). "We found that the mRNA expression level of ADCK2 did not depend on the mutational status of melanoma cells." (PMID 35205819, 2022). "In this study, we could demonstrate that ADCK2 affects different properties of melanoma cells and that these effects are mediated via MYL6." (PMID 35205819, 2022). "Understanding the consequences of the downregulation of ADCK2 in melanoma cells could additionally open up new possibilities for therapeutic approaches." (PMID 35205819, 2022). "In order to investigate the role of ADCK2 in melanoma, we checked the endogenous mRNA expression levels of nine melanoma cell lines (BRAF and NRAS WT: MeWo, BRAF-mutated: WM2664, A375, HT144, SkMel28, C32 and NRAS-mutated: SkMel30, SkMel103, SkMel173) and normal human melanocytes (NHM)." (PMID 35205819, 2022). "Additionally, the knockdown of MYL6 mitigated the effects of ADCK2 expression in melanoma cells." (PMID 40565246, 2025).
melanoma (continued). "Additionally, we stably overexpressed ADCK2 in SkMel28, A375, SkMel30 and MeWo cells with the help of a lentiviral expression construct in order to determine if this also affects the cell viability of melanoma cells." (PMID 35205819, 2022). "Our results allow the conclusion that ADCK2 could act as a tumor suppressor in melanoma." (PMID 35205819, 2022). "Furthermore, we demonstrated that a knockdown of ADCK2 led to a more aggressive phenotype of melanoma cells, suggesting that ADCK2 might be a suitable prognostic marker." (PMID 35205819, 2022). "ADCK2 could control the migration of melanoma cells by affecting the formation of NM2s via MYL6." (PMID 35205819, 2022). "To further investigate if the effect of ADCK2 on viability and migration was mediated via MYL6, we ectopically overexpressed ADCK2 while simultaneously knocking down MYL6 in melanoma cell lines." (PMID 35205819, 2022). "A gene expression array confirmed a positive correlation between ADCK2 expression and RAB2A (Ras-related protein Rab-2A) and MYL6 expression in different melanoma cell lines." (PMID 35205819, 2022). "Our results show that ADCK2 has a considerable negative effect on migration and invasion of melanoma cells and, thus, might act as a tumor suppressor." (PMID 35205819, 2022). "Furthermore, we found a tendency for a slightly reduced expression of ADCK2 in melanoma cell lines compared to NHM, which, however, was not significant except for the cell line C32." (PMID 35205819, 2022).
basal cell carcinoma (1 paper, 2022). A carcinoma involving the basal cells. "KEGG pathway analysis further revealed that DEGs of basal cell carcinoma, cell cycle and DNA replication cascades were enriched in the ADCK2-high NSCLC." (PMID 36439873, 2022).
brain tumor (1 paper, 2024). "ADCK2 is necessary for cell proliferation of GBM, a fatal primary brain tumor containing countless genetic and epigenetic alterations." (PMID 38701413, 2024).
breast NET (1 paper, 2022). "In breast NETs, we found ADCK2 missense pathogenetic or unknown variants in 5/53 (9.4%) cases, four of them being located in the same codon (Phe385Leu)." (PMID 36085291, 2022). "Four of the five ADCK2 pathogenetic or unknown variants observed in breast NETs were located in the same codon (Phe385Leu)." (PMID 36085291, 2022). "There are, however, certain differences between breast NET and IDC mutational profiles, as exemplified by those in the MEN1 and ADCK2 genes." (PMID 36085291, 2022). "After observing that ADCK2 pathogenetic or unknown variant rates were substantially different between breast NET and IDC, we determined also the mRNA and protein levels of ADCK2 in the breast NET samples." (PMID 36085291, 2022).
cervical cancer (1 paper, 2022). A primary or metastatic malignant neoplasm involving the cervix. "Lower viability after knocking down ADCK2 could also be confirmed in several cell lines from breast, lung and cervical cancer and is assumed for retinoblastoma." (PMID 35205819, 2022).
fibrosarcoma (1 paper, 2022). A malignant mesenchymal fibroblastic neoplasm affecting the soft tissue and bone. "In addition, a fusion of BRAF and ADCK2 has been detected in infantile fibrosarcoma." (PMID 35205819, 2022).
Klippel-Feil syndrome (1 paper, 2017). A congenital, musculoskeletal condition characterized by the fusion of at least two vertebrae of the neck. "One of the promoter candidate genes was ADCK2 (AarF domain containing kinase 2), mutation of which is associated with Klippel-Feil syndrome, a disease involving segmentation defects during early development." (PMID 28966120, 2017).
lipid metabolism disorder (1 paper, 2019). "The defect in mitochondrial FA β-oxidation in Adck2+/− mice was consistent with the significant decrease of β-hydroxybutyrate and glycerol, and a trend of cholesterol increase in plasma of Adck2+/− mice supported a lipid metabolism disorder." (PMID 31480808, 2019).
prostate adenocarcinoma (1 paper, 2012). "Depletion of PRKAR2B, ADCK2, TRPM7 and TRIB2 significantly decreased HIF-1α accumulation in LNCaP, an androgen-sensitive human prostate adenocarcinoma cell line with low invasive potential." (PMID 22355351, 2012).
sarcopenia (1 paper, 2024). Progressive decline in muscle mass due to aging which results in decreased functional capacity of muscles. "Notably, Adck2+/− embryos have defective muscle formation, previously associated with a premature onset of robust muscle wasting and sarcopenia.S16 We demonstrate a disturbed ageing process in skeletal muscle from Adck2+/− mice, affecting metabolic and structural factors." (PMID 39354863, 2024).